ENSG00000279284 ( gene)
Diseases named in the same sentence as ENSG00000279284 in open-access papers (continued):
Sharing a sentence is not in itself a finding about the gene and the disease.
tumor (continued). "Indeed, it has been shown that miR-96 (7q32.2) can function either as oncogene or tumor suppressor gene in different tumor types." (PMID 25071021, 2014). "Ectopic expression of HSPB7 significantly impaired colony-forming ability for 5 RCC cell lines, indicating that HSPB7 may function as a tumor suppressor gene." (PMID 24585183, 2014). "Although the activation of Stat5 has been associated with tumourigenesis of several solid tumours, in the liver, Stat5 has a role as tumour promoter but it seem to have also a potential role as tumour suppressor gene; therefore, the role of Stat5 in hepatocarcinogenesis is still debated." (PMID 25225571, 2014). "Since miR-30b was either up-regulated or reduced in different cancers, we could draw a conclusion that miR-30b may play different roles as an oncogene or a tumor suppressor gene in various cancers." (PMID 25170877, 2014). "Based on that, miR-601 could serve as a putative tumor suppressor gene, whilst miR-34a as an oncogene." (PMID 25551588, 2014). "These opposing findings substantiate the hypothesis that miR-141 may play different roles as an oncogene or a tumor suppressor gene in different cancer types." (PMID 24551096, 2014). "Finally, the klotho gene encoding the obligate co-receptor for FGF-23 is also a putative tumour suppressor gene, further implying the link between Pi regulation and carcinogenesis." (PMID 23706176, 2013). "RARRES1 is a retinoic acid receptor that acts as a vital tumor suppressor gene." (PMID 23922792, 2013). "According to previous studies, CDKN2B may act as a tumor suppressor gene and a potential effector of TGFβ-induced cell-cycle arrest." (PMID 24098334, 2013). "SLIT2 has been postulated for several years to act as a tumour suppressor gene in several cancers." (PMID 23671423, 2013). "Furthermore, autophagy is a novel evolutionarily conserved function of the PKR pathway that is targeted by viral virulence gene products and in cancer where anti-tumor effects induce autophagosome formation through PKR activation." (PMID 24330807, 2013). "The location of human SF-1 in the region of 9q33 supports our hypothesis that SF-1 is a candidate tumor suppressor gene in the ovary and that abolished or aberrant SF-1 expression in OSE cells may promote tumor growth." (PMID 23291911, 2013). "The NIH3T3 transformation data also suggest that Mybbp1a might be able to act as a tumor suppressor gene in some contexts." (PMID 23056166, 2012). "One of the reported targets of miR-205 is a critical tumor suppressor gene, PTEN." (PMID 22514717, 2012). "In such tumours, E-cadherin acts as a typical tumour suppressor gene." (PMID 22973534, 2012). "Notably, the roles of miR-100 in different cancers are quite contradictory as it can behave either as an oncogene or a tumor suppressor gene, depending on the tumor type examined." (PMID 23173870, 2012). "Genetic analysis of tumor samples indicates that FH acts as a tumor suppressor gene." (PMID 22087286, 2011). "Additionally, Fhit suppresses tumourigenicity in cancer cell lines which implies conclusively that FHIT is a bona fide tumour suppressor gene." (PMID 22295218, 2011). "Interestingly, the overlap of all three tumor groups included the region containing INTS6, an annotated tumor related gene (also known as DICE1, Protein deleted in cancer 1)." (PMID 20735817, 2010). "In addition, we identified relevant cancer-related target genes and pathways targeted by miR-218, supporting a potential role as a tumour suppressor gene for NSCLC, especially SCCs." (PMID 20838434, 2010). "THBS4 may act as a tumour suppressor gene, demonstrated by its suppression of tumour colony formation in vitro." (PMID 20846368, 2010). "These suggest that IGF-I may promote tumor cell growth, while IGFBP-3 acts as a tumor suppressor gene." (PMID 19549343, 2009).
tumor (continued). "If a particular miRNA targets key tumor suppressor genes, it is supposed to be an oncogene; but, if a miRNA targets an oncogene, it might be viewed as a tumor suppressor gene." (PMID 18079974, 2007). "Here I discuss some facts and thoughts that support the idea that p73 could still be a tumor suppressor gene." (PMID 17407586, 2007). "The facts that TA-p73 can induce apoptosis and it is hypermethylated in tumors of lymphoid origin indicate that this could function like a tumor suppressor gene." (PMID 17407586, 2007). "Since the hyd gene, which encodes the proposed Drosophila ortholog of EDD, was originally identified as a tumor suppressor gene, these findings indicate that deregulation of EDD activity could contribute to tumor development." (PMID 18047743, 2007). "However, one note of caution must be added in that STIM1 was initially identified as a candidate tumour suppressor gene and the consequences therefore of long term inhibition of STIM1 expression need to be explored further." (PMID 16987424, 2006). "PRKAR1A is a key component of the cAMP signaling pathway that has been implicated in endocrine tumorigenesis and could, at least partly, function as a tumor suppressor gene." (PMID 16756677, 2006). "The amplification of this gene seems contrary to its putative role as a tumor suppressor gene." (PMID 16004614, 2005). "A novel finding here was the increased expression at 1 dpi of CCAAT/enhancer binding protein (C/EBP)-δ belonging to C/EBP (bZIP) family, which couples extracellular signal transduction pathways to numerous cellular processes and is a potential tumour suppressor gene." (PMID 16318630, 2005). "It indicated that TSHZ3 may act as a tumor suppressor gene in LUAD." (PMID 40264773, 2025). "Thus, it is conceivable that ADAR2 may serve as a tumor suppressor gene, regulating glycolipid metabolism and proliferation in GBM cells." (PMID 39794701, 2025). "DDX3 may act as either an oncogene or a tumor suppressor gene in different types of cancer." (PMID 39543456, 2025). "Therefore, DDX3 may function as an oncogene or a tumor suppressor gene by regulating the expression of cancer‐related miRNAs in human cells." (PMID 39543456, 2025). "Here, we evaluated the tumor morphology and immunohistochemical expression of CDH17 and CLDN18 in 25 CD-SBNs and potential relationships with gastric differentiation as indicated by MUC5AC and MUC6 immunohistochemistry, wnt pathway mutations, and mismatch repair gene protein immunohistochemistry." (PMID 39164422, 2025). "Additionally, the molecular mechanism by which LSAMP functions as a tumor suppressor gene by modulating known oncogenic pathways may provide new opportunities for treating patients with LSAMP associated malignancies." (PMID 39595156, 2024). "Therefore, unlike DKK 1, 2, and 4, there is still some debate about whether DKK3 is an oncogene or a tumor suppressor gene." (PMID 37149563, 2023). "In conclusion, our findings uncovered that CASC2 could act as a tumor suppressor gene and inhibit cell proliferation, migration, and invasion through binding to miR-155, thus increasing the expression of its target gene SOCS1, demonstrating the ceRNA function of CASC2." (PMID 36816357, 2023). "In summary, ZDHHC11B may act as a tumor suppressor gene in LUAD." (PMID 37434393, 2023). "This is probably because OAS1 may act as a tumor suppressor gene in other biological processes, such as cell proliferation, metastasis and drug resistance in BLCA, although OAS1 protects an immunosuppressive TME in BLCA, and these guesses need to be verified in the future." (PMID 37746262, 2023). "Therefore, we hypothesized that FN1 in tumor cells may be a key macrophage-regulated ECM gene that promoted enzalutamide resistance in bone-metastatic PC." (PMID 36749798, 2023). "Hence, our data suggest that KLF2 may serve as a tumor suppressor gene in the majority of common tumors." (PMID 37123417, 2023). "Evidence is accumulating that PRUNE2 might act as a tumor suppressor gene." (PMID 36645410, 2023).
tumor (continued). "Previous studies indicated that GATA4 might act as a putative tumor suppressor gene." (PMID 36588538, 2022). "Therefore, we assumed that the target gene of L3MBTL2 might be a tumor suppressor gene with a certain role in cancer." (PMID 35521536, 2022). "However, KRT17 is underexpressed in some tumors, and it is considered that KRT17 may play a role as a tumor suppressor gene in these tumors." (PMID 35281081, 2022). "YTHDF1 could act as an oncogene or a tumor suppressor gene in tumors." (PMID 35197112, 2022). "Therefore, combining the results from cell viability data in vitro, CYP39A1 might serve as a tumor suppressor gene in HCC." (PMID 35003516, 2021). "The results show that ANKRD11 may be a tumor suppressor gene." (PMID 34604130, 2021). "As a tumor-related gene, TXNDC12 may be used as a new prognostic judgment molecule." (PMID 34629960, 2021). "Therefore, large-scale studies are required to fully dissect the functions of PDK4 in tumor progression and the underlying mechanisms in a variety of human tumor types, which will explain why PDK4 acts as an oncogene or a tumor suppressor gene in various cancers." (PMID 32489458, 2020). "Considering the extensive expression of Porf-2 in the brain and many peripheral tissues, including testes, liver, kidney, prostate, and placenta, and its downregulation in several human tumors, Porf-2 may function as a potential tumor suppressor gene in several systems." (PMID 32676454, 2020). "Although GEMMs are suitable for investigation of whether a certain gene alteration induces tumor formation or whether an altered gene functions as an oncogene or a tumor suppressor gene, the generation and maintenance of such models are time-consuming and require a considerable amount of effort." (PMID 33348616, 2020). "Additionally, a high expression of WT1 (Wilms tumor gene) mRNA in the aqueous humor was discovered." (PMID 31977890, 2020). "However, SPP2 is generally lowly expressed in tumors, suggesting that SPP2 may serve as tumor suppressor gene." (PMID 31849319, 2019). "Therefore, it is tempting to speculate that in CRC, MSX1 represents a tumor-promoting gene with some essential function." (PMID 30733598, 2019). "Interestingly, Notch-1 may act as an oncogene or a tumor suppressor gene even within the same tumor type, and recently, it has been implicated in induction of cellular senescence mediated by p16 and p21." (PMID 29618945, 2018). "Moreover, BMP-2 is considered a putative tumour-suppressor gene in several cancer types." (PMID 30013089, 2018). "The functional studies indicated that HADHB might act as a tumor suppressor gene." (PMID 29507648, 2018). "In addition to regulation of myeloid cell activation and various inflammatory diseases, role of KLF2 is also emerging as a potential tumor suppressor gene owing to its roles in the inhibition of proliferation, migration and angiogenesis and in the induction of apoptosis, senescence and adhesion." (PMID 29125549, 2017). "Furthermore, overexpression of AP-2α has been shown to suppress tumorigenicity suggesting that AP-2 α may function as a tumor suppressor gene." (PMID 29100274, 2017). "Taken together, HOTAIRM1 maybe function as a tumour suppressor gene in CRC." (PMID 27307307, 2016). "Furthermore, the Y chromosome gene TMSB4Y may be a tumor suppressor gene that normally functions through its direct interaction with β-actin, which in turn regulates cell morphology and cell proliferation." (PMID 26702755, 2015). "Finally, our results suggest that Wnt7A is possibly a novel tumor-suppressor gene in MPM." (PMID 25632963, 2015).
tumor (continued). "However, a study reported that HOTAIR induces repressive chromatin status by promoting the formation of H3K27, suggesting that HOTAIR may function as a tumor suppressor gene by inhibiting proliferation of cancer stem cells." (PMID 25303230, 2014). "Thus, hBD-2 is likely to be a putative tumor-suppressor gene." (PMID 24927104, 2014). "What’s more, there are evidences to believe that GSTP1 methylation could trigger “epigenetic catastrophe” which involves hypermethylation of associated genes including APC (a tumor suppression gene), and RAR-beta (tumor suppressor gene involved in cell cycle and apoptosis)." (PMID 24086370, 2013). "Our results suggested that the LEPREL1 might be a tumor suppressor gene." (PMID 24319452, 2013). "Our study provides evidence that GPER-1 may be a tumor suppressor gene." (PMID 23849542, 2013). "On the other hand, TRIB2 may serve as a tumor suppressor gene." (PMID 24191888, 2013). "As a tumor suppressor gene, miR-122 is downregulated in HCC cell lines and tumor tissues, leading to the activation of the Wnt/β-catenin pathway, thereby promoting the formation and progression of HCC." (PMID 39935848, 2024). "Treatment with the methylation inhibitor 5‐aza‐dC promotes GSDME expression and inhibits tumor cell proliferation and tumorigenesis, suggesting GSDME as a novel tumor suppressor gene in CRC." (PMID 37125240, 2023). "However, BCL2 may function as an oncogene or as a tumor suppressor gene in various types of cancer." (PMID 38003498, 2023). "Thus, we speculated that SIRT5 may be an important tumor suppressor gene." (PMID 37096064, 2023). "Only in one primary tumor, we detected cn-LOH at the chromosomal region 3p21.31-p21.1, which harbors the tumor suppressor gene von Hippel-Lindau (VHL)." (PMID 38010391, 2023). "In accordance with the result that IGF-2 promotes the growth and proliferation of tumor cells, IGF-2R is considered to be a tumor suppressor gene during cancer occurrence and development." (PMID 36358907, 2022). "For example, DEFB1, the human antimicrobial peptide defensin β 1, is considered as a potential tumor suppressor gene and has been shown to mediate PI3K/mTOR signaling, thereby leading to death of tumor cells." (PMID 35938006, 2022). "Thus, we hypothesized that FBXW7 may act as a tumor-suppressive gene in CC." (PMID 35094292, 2022). "An epigenetic study of HCC also confirmed ESR1 as a tumor suppressor gene, with up to 83% of HCC patient tumors demonstrating ESR1 promoter hypermethylation and predicting tumor progression." (PMID 34881186, 2021). "While many miRNAs have been demonstrated to inhibit tumor formation and/or growth, the tumor suppressor miRNAs mentioned in both the literature and in this review may not be a “classic” tumor suppressor gene that has been demonstrated to cause tumor formation after biallelic inactivation." (PMID 33562727, 2021). "However, it is still unknown whether P63 is a tumor suppressor gene or an oncogene." (PMID 33936229, 2021). "In contrast, when transplanted subcutaneously in mice, three HOMCs with NF2 knockdown formed a tumor mass, confirming that NF2 is an important tumor suppressor gene in MM cells." (PMID 34663305, 2021). "Pertaining to metastasis, research shows that suppression of the tumor suppressor gene, epithelial cadherin (CDH1), is a key factor in EMT as it allows for the tumor cell to detach from its primary tumor site and metastasize in a secondary site." (PMID 32316322, 2020). "The tumor growth assay showed that LINC01088 significantly inhibited tumor growth, implying that LINC01088 was a tumor suppressor gene, although its mechanism remained unclear." (PMID 29440672, 2018). "Thus, whether UPP acts as an oncogene or tumor suppressor gene mainly depends on the context." (PMID 27121050, 2016). "Moreover, many studies have indicated CSMD1 could be a tumor suppressor gene." (PMID 26076954, 2015).
tumor (continued). "As a tumor suppressor gene, PTCH1 inhibits tumor cell growth and motility by blocking the Hh signaling pathway." (PMID 24961235, 2014). "To explore TAGLN and HDAC2 expression in GBM patient surgical specimens, we performed IHC staining and observed that HDAC2 (which is a hypoxia‐related gene), TAGLN, CA9 (a hypoxic marker), and HIF1α were all located in GBM tumor cell nuclei and highly expressed in pseudopalisades (upper)." (PMID 38087889, 2024). "Downregulation of nCLU expression was found to enhance tumor formation, therefore leading to the conclusion that CLU might also be a tumor and metastasis suppressor gene." (PMID 37685987, 2023). "First, we found that the expression level of KLF7 is higher in PCa tissues of patients, and the expression of KLF7 is positively correlated with tumour-promoting gene IL-6, while it is negative correlated with another tumour-suppressor gene p21." (PMID 37170248, 2023). "Many recent studies have shown that SASH1 is ubiquitously expressed in most normal tissues but is decreased or absent in tumor tissues, supporting its function as a tumor inhibitory gene." (PMID 36286186, 2023). "Although FEZ2 is dysregulated in some types of cancers, there is no research mentioned that FEZ2 functions as an oncogene or tumor suppressor gene in PDAC." (PMID 35036176, 2022). "SFRP2 is a secreted key inhibitor of non-canonical Wnt signaling and is considered a tumor suppressor gene depending on the organ/cellular context." (PMID 35892888, 2022). "With regard to HCG11, it has been identified to be aberrantly expressed in some cancers and function as an oncogene or a tumor suppressor gene, not including OS yet." (PMID 34518440, 2021). "The presence of the RheoSwitch construct in the B16-RS cells enabled us to amplify and detect the RheoActivator element, which served as a tumor cell-specific marker, and was normalized to the expression of the 60S acidic ribosomal protein P0 (RPLP0), used as a house-keeping gene." (PMID 34830742, 2021). "AMPK suppresses tumor survival through inhibition of mTOR by increasing the expression of p-TSC2, a tumor suppressor gene, and leads to the inactivation of AKT and lipopolysaccharide (LPS)-induced IL-6/JAK2/STAT3 signaling in triple-negative breast cancer (TNBC)." (PMID 31952344, 2020). "Our studies in different RCC cell lines indicated that the absence of the tumour suppressor gene pVHL induced a decrease in the expression of the tumour and angiogenesis inhibitor TSP-1." (PMID 31980715, 2020). "In respect to this, ELF2B acts in a dominant negative fashion compared to ELF2A and as a putative tumour suppressor gene." (PMID 28351373, 2017). "Furthermore, it has been reported that LIFR is a tumor suppressor gene in HCC and its down-regulation in tumor tissues is mostly dependent on promoter hypermethylation." (PMID 25749520, 2015). "In this picture, CD146 appears as a prometastatic factor associated with poor-prognosis histoclinical features, rather than as a tumor suppressor gene." (PMID 19123925, 2009). "In addition to that, ECM‐related gene such as MMP9 and MUC5B were prominently upregulated in poorly group, indicating that the expression of these genes in macrophages plays a pivotal role in influencing tumour differentiation." (PMID 40847563, 2025). "In addition, Lu/BCAM may act as a tumor suppressor gene, as demonstrated in thyroid cancer where Lu/BCAM is downregulated and negatively correlated with tumor growth." (PMID 40332051, 2025). "Similarly, miR-20b, a member of the miR-106b-25 cluster cannot be classified as either an oncogene or tumor suppressor gene." (PMID 36994208, 2023). "Our results suggest that in LGG, unlike in GBM, DKK3 may also act as a tumor suppressor gene to some extent in relation to Wnt/β-catenin signaling." (PMID 37149563, 2023).